NOX4 (NADPH oxidase 4)
Diseases named in the same sentence as NOX4 in open-access papers (continued):
Sharing a sentence is not in itself a finding about the gene and the disease.
atherosclerosis (continued). "Conversely, NOX4 has been shown to exert protective effects on atherosclerosis development, in mouse models." (PMID 28612009, 2017). "A recent report showed that aged ApoE−/− and ApoE−/− /p47phox−/− mice that developed atherosclerosis and vascular dysfunction were characterized by mitochondrial dysfunction related with an upregulated expression of NOX4 in VSMCs." (PMID 28230726, 2017). "NOX-4 expression and activity during the aging process enhances cellular and mitochondrial oxidative stress, vascular inflammation, dysfunction, and atherosclerosis." (PMID 28878685, 2017). "Previous studies showed that activated TLR4/MyD88 upregulated NOX4 expression in LPS-activated cells and lead to atherosclerosis." (PMID 27891092, 2016). "The current knowledge regarding the involvement of Nox4 in atherosclerosis mostly derives from interventions in cell culture." (PMID 25866599, 2015). "Elevated Nox4 expression was previously reported in many cardiovascular diseases including atherosclerosis, pulmonary artery hypertension, stroke, and heart failure." (PMID 25298619, 2014). "In numerous cardiovascular diseases, such as hypertension, atherosclerosis, pulmonary and cardiac fibrosis, cardiac failure, stroke and diabetes, the expression level of Nox4 is elevated." (PMID 23125837, 2012). "Laminar flow which has been shown to be protective against atherosclerosis actually decreases Nox4 expression whereas oscillatory shear stress increases it." (PMID 23125837, 2012). "In this context, the balance of NOX4 activity must be considered: both excessive activation and loss of NOX4 are detrimental, necessitating a more thorough approach to the development of NOX4 suppression strategies in the context of ox-LDL-induced atherosclerosis." (PMID 41511286, 2025). "Inhibiting NOX4 or mitochondrial dysfunction could alleviate vascular inflammation and atherosclerosis, preserving plaque integrity." (PMID 38975335, 2024). "Elevated NOX4 expression in the aortic wall and vascular smooth muscle cells, isolated from aging aortas, has been reported in connection with aortic stiffening and atherosclerosis in hypercholesterolemic mice." (PMID 39457110, 2024). "Targeting NOX4-dependent mitochondrial ROS holds promise in atherosclerosis management." (PMID 38975335, 2024). "Additionally, NOX4 was shown to mediate vasoprotection under pathological conditions such as hypertension and atherosclerosis." (PMID 38790608, 2024). "Therefore, the observed increase in atherosclerosis cannot be attributed to metabolic changes, which underscores the role of NOX4 in the age-related progression of atherosclerotic lesions." (PMID 38975335, 2024). "In a mouse model study in 2018, it was found that the inhibition of NOX-4 could improve inflammation under conditions of atherosclerosis." (PMID 38027009, 2023). "This study demonstrated the value of butyrate in preventing NOX-4-induced atherosclerosis." (PMID 38027009, 2023). "Furthermore, QUR protected against ischemia/reperfusion-mediated cardiac and neural apoptosis and high-fat diet (HFD)-induced atherosclerosis by suppressing NOX4." (PMID 36838869, 2023). "Furthermore, NOX4 has been shown to have protective anti-inflammatory effects in atherosclerosis and is down regulated in patients with atherosclerosis and diabetes, and in mouse models of atherosclerosis." (PMID 35601109, 2022). "NOX4 is a double‐edged sword in atherosclerosis that can both relieve and exacerbate the disease." (PMID 35386842, 2022). "In mouse models of atherosclerosis, NOX4‐derived ROS were essential for vessel homeostasis." (PMID 35386842, 2022). "Recent studies have shown that NOX4 may prevent the development of atherosclerosis and endothelial dysfunction in apolipoprotein E–deficient (apoE–/–) mice." (PMID 35617030, 2022). "In addition to NOX4, other NOXs have also been found to be aberrantly upregulated in atherosclerosis." (PMID 35386842, 2022).
atherosclerosis (continued). "Investigate the role of type 4 isoform (NOX4) in human and mouse atherosclerosis." (PMID 36359402, 2022). "However, a possible protective role of NOX4 in atherosclerosis has been described since this isoform produces low levels of H2O2, reducing the inflammation status and, consequently, atherosclerosis severity." (PMID 32664383, 2020). "Furthermore, EC-specific overexpression of the human NOX4 dominant negative P437H mutant led to an acceleration in atherosclerosis development and a cell-specific decline in NOX4 expression in the EC vs SMC of STZ-diabetic mouse vessels." (PMID 32923955, 2019). "Furthermore, NOX4 has been linked to smooth muscle cell (SMC) migration and proliferation, which are essential steps in the development of atherosclerosis." (PMID 32923955, 2019). "Increased Nox4 expression was also correlated with atherosclerosis severity in human subjects." (PMID 29710840, 2018). "The protective role of Nox4 in atherosclerosis has been also demonstrated in Nox4−/− animal models." (PMID 29710840, 2018). "Apart from NOX2, also NOX4, NOX5, p22phox, and, to a lesser extent, NOX1 may be implicated in the pathogenesis of atherosclerosis." (PMID 29430280, 2017). "Somewhat contradictorily, NOX4 was protective in a renal fibrosis model, and there is evidence from mice and patient data that NOX4 may be protective against atherosclerosis." (PMID 28670577, 2017). "A similar modulatory effect of Nox4 in other disease setting (e.g., in atherosclerosis or cancer) could also be pathophysiologically relevant." (PMID 29445778, 2017). "The flagellin-induced Nox4 activation stimulates the expression of various pro-inflammatory mediators, leading to the adhesion and trans-endothelial migration of monocytes which are the key events of atherosclerosis." (PMID 27146088, 2016). "Moreover, we demonstrated that the Nox4-deficient ApoE KO mice exhibited significant protections against rFliC-mediated atherogenesis indicating that TLR5-dependent Nox4 activation is critical for the development of atherosclerosis." (PMID 27146088, 2016). "In human atherosclerosis, Nox4 expression is increased in intimal lesions of coronary arteries." (PMID 23125837, 2012). "However, in experimental atherosclerosis, Nox4 protein levels are unchanged in the aorta of genetically susceptible mice or in primate models." (PMID 23125837, 2012). "Despite these observations, a clear role for Nox4 in atherosclerosis remains to be determined." (PMID 23125837, 2012). "Additionally, NOX-4 is another target for the treatment of atherosclerosis." (PMID 38027009, 2023). "Genes involved in fluid shear stress and atherosclerosis include IL1β, TNF, MMP9, AKT1, and NOX4; genes associated with AGE-RAGE signaling pathway in diabetic complications include AKT1, IL1β, and NOX4; while genes associated with HIF signaling pathway contain STAT3, NOX4, NFκB, and MAPK1." (PMID 36192741, 2022). "Nox4 has been shown to have protective effects in many pathophysiological settings including during chronic pressure overload-induced remodelling, myocardial ischaemia–reperfusion, hind-limb ischaemia, kidney injury, remodelling after myocardial infarction, and atherosclerosis." (PMID 31821410, 2021). "In the vasculature, NOX1, NOX2 and NOX4 are the isoforms predominantly expressed by different cell types in the intima, media and adventitia layers and may contribute to oxidative stress in both human and experimental atherosclerosis." (PMID 32824091, 2020). "Consequently, the actions of catalpol protecting against HCY-induced injuries in HAECs by inhibiting Nox4/ROS-NF-κB pathway and ER stress might be used in the treatment and/or prevention of atherosclerosis." (PMID 30315526, 2019).
atherosclerosis (continued). "Moreover, injection of recombinant FliC (rFliC) into Nox4ApoE DKO mice fed high-fat diets (HFDs) resulted in significantly decreased atherosclerotic plaque sizes compared with injection into ApoE KO mice, suggesting that Nox4 has proatherogenic activity in rFliC-mediated atherosclerosis." (PMID 31292433, 2019). "NOX4 is thought to play a role in the regulation of cell growth or cell survival in endothelial cells, suggesting that NOX4 may play an essential role in the formation of atherosclerosis." (PMID 31547608, 2019). "The contrasting findings in the setting of stroke compared to the setting of atherosclerosis highlight that NOX4 can play both a detrimental and protective role in disease development and that this may largely depend on the specific nature of the vessel, that being macrovascular or microvascular." (PMID 32923955, 2019). "It is unknown whether altered subcellular localization in conditions of stress, together with oxidation of cysteine residues in the E-loop and/or interaction with unknown adaptors, may promote Nox4-mediated superoxide production during atherosclerosis development." (PMID 29710840, 2018). "However, the role of NOX4 in atherosclerosis is controversial." (PMID 27891092, 2016). "In atherosclerosis, NOX1 is elevated early but declines later, while NOX4 increases in advanced stages." (PMID 39867658, 2024). "In aged mice with atherosclerosis, TGF-β1 upregulates NOX4, which in turn activates CCL2 expression in VSMCs, further linking aging to increased CCL2 expression and inflammation related to atherosclerosis." (PMID 39201480, 2024). "NOX4 (NADPH oxidase 4) expression increases with age, correlating with mitochondrial dysfunction, inflammation, and atherosclerosis." (PMID 38975335, 2024). "It has been established that NOX4/ROS, which is primarily triggered by TNF-α, plays a significant role in the development of atherosclerosis." (PMID 38028719, 2023). "The expression of NOX4 has been shown to be induced in VSMC mitochondria and vasculature and is correlated with an increased aortic stiffening and atherosclerosis in aged mice." (PMID 36552585, 2022). "Interestingly, the NOX4-dependent effects that underlie docetaxel-induced vascular dysfunction may not mirror the role of this homolog in atherosclerosis." (PMID 35617030, 2022). "NOX1, NOX2, NOX4, and NOX5 appear to be of particular interest for atherosclerosis, but, unfortunately, data which demonstrate the particular functions and their mechanisms are disparate." (PMID 32664404, 2020). "Important stressors with a relevant role in atherosclerosis (e.g., AngII, advanced glycation end products -AGE-, inflammatory molecules, and NOX4 activation) are known inducers of vascular cell senescence." (PMID 28612009, 2017). "Cardiovascular dysfunction, as well as atherosclerosis has been related with an increased expression of NOX2, NOX4 and NOX5, but only at early stages." (PMID 28230726, 2017). "In conclusion, H2O2 generation through Nox4 activation plays a significant role in mediating flagellin-induced atherosclerosis, and we first verified a link between TLR5 and atherosclerosis." (PMID 27146088, 2016). "We conclude that TLR5-dependent Nox4 activation and subsequent H2O2 generation play critical roles for the development of atherosclerosis." (PMID 27146088, 2016). "Gene deletion of nNOS in ApoE−/− mice accelerates atherosclerotic plaque formation, while overexpression of Nox4 forming H2O2 reduces the expression of profibrotic and pro inflammatory markers inhibiting vascular remodeling in mice prone to atherosclerosis." (PMID 27435231, 2016).
atherosclerosis (continued). "The observed endothelial dysfunction and resulting atherosclerosis, however, was more profound in mice lacking Nox4." (PMID 37627585, 2023). "However, up-regulated vascular smooth muscle cell (VSMC) NOX4 correlates with VSMC dysfunction and plaque instability, whilst VSMC NOX4 deletion attenuates western-diet–induced atherosclerosis." (PMID 33881501, 2022). "The expression patterns of miR-363-3p, NADPH oxidase 4 (NOX4), and p38 MAPK/p-p38 MAPK were examined in an established atherosclerosis (AS) model in C57BL/6 mice and in isolated coronary arterial endothelial cells (CAECs) after gain- or loss-of-function experiments." (PMID 33744854, 2021). "In contrast, NOX-4 was found exclusively in non-phagocytic cells with NOX-4 being highest in stage IV atherosclerosis and dramatically decreased in the most complicated plaques that are characterized by fibrosis and a reduction in intimal VSMC." (PMID 29099757, 2017). "Inhibition of NOX1, implicated in the pathogenesis of restenosis and atherosclerosis, has been shown to significantly inhibit neointimal formation, and unlike NOX2 and NOX4, has been shown to be upregulated by bFGF in rat and mouse aortic SMCs." (PMID 25144362, 2014). "In aged Apoe-/- mice, inhibition of NOX4 activity using GKT137831 significantly reduced macrophage mitochondrial ROS and improved mitochondrial function, resulting in decreased CD68+CD80+ and increased CD163+CD206+ lesion macrophage proportion and attenuated atherosclerosis." (PMID 38975335, 2024). "Concerning Nox4 expression, we did not observe significant changes after PS5 administration, which could be consistent with the protective role of Nox4 against atherosclerosis in murine models." (PMID 32824091, 2020).
Hypertension (85 papers, 2010 to 2026). The presence of chronic increased pressure in the systemic arterial system. "For example, NOX4 deficiency is associated with hypertension and potentiation of endothelial dysfunction and vascular remodeling in a mouse model of hypertension." (PMID 40725005, 2025). "While the molecular studies of NOX1 and NOX2 showed their role in promoting hypertension, NOX4 activity has been linked to a protective function." (PMID 34205998, 2021). "Previous studies indicate the link between oxidative stress via NOX1, NOX2, and NOX4 caused by these substances involved in hypertension." (PMID 34440716, 2021). "The progression of hypertension observed in 3-month-old SHRs, was associated with significant elevation of both Nox1 and Nox4 mRNA level in the aortas." (PMID 33131726, 2020). "NOX4 overexpression in endothelial cells is associated with vasodilatation and reduced blood pressure, suggesting that it has a protective role in hypertension and the related complications." (PMID 29430280, 2017). "Mounting evidence demonstrates that NOX4 plays an important role in the development of pulmonary vascular remodeling and hypertension caused by hypoxia." (PMID 28594389, 2017). "In accord with our observations, decreased Nox4 expression has been reported in Ang II infused rats, which develop hypertension in association with increased oxidative stress." (PMID 24025423, 2013). "Nox1, Nox2, Nox4, and Nox5 of the Nox family are associated with oxidative stress in hypertension." (PMID 39974735, 2025). "NOX2 and NOX4 in the hypothalamic paraventricular nucleus are key sources of aldosterone, leading to ROS release, causing sympathetic excitation, and contributing to the development of hypertensive disease." (PMID 36407440, 2022). "NOX1 and NOX4 mediate signaling pathways that promote smooth muscle cell proliferation, differentiation, and migration, causing vascular remodeling and exacerbating the progression of atherosclerosis and hypertension." (PMID 36407440, 2022). "Angiotensin II type 1 receptor activation and hypertension are linked to increased expression of Nox1 and Nox4 that could lead to vascular damage during chronic hypertension." (PMID 27774507, 2016). "ANG increased BP and proteinuria (p = 0.02), water intake (p < 0.001), urinary output, heart weight, and aortic NOX4 (p < 0.01), confirming hypertension and oxidative stress." (PMID 41204447, 2025). "The expression of NOX4 in the context of hypertension has been repeatedly studied in several model systems and results have proven to be enigmatic." (PMID 41178013, 2025). "The production of ROS by NOX4 is the molecular basis of AS, hypertension, and other chronic diseases." (PMID 39529974, 2024). "Studies have proposed that Nox4 expression increases in the endothelium, mediating ROS production and vascular dysfunction in human arteries and mouse aortas during hypertension, in human skeletal muscle feed arteries during aging and type 1 diabetic mice." (PMID 37501791, 2023). "Further, AMPK activation by Sesn2 can influence overactive NOX4, decreasing the ROS production exhibited in hypertension." (PMID 37510117, 2023). "lncRNA FENDRR plays a positive role in essential hypertension by regulating the miR-423-5p/Nox4 axis, inhibiting cell proliferation and migration and accelerating cell apoptosis, thereby promoting the dysfunction of human umbilical vein endothelial cells." (PMID 37396592, 2023). "A previous study has shown that hypertension-induced kidney injury in rats is mediated by activation of the AT1R/Nox4/oxidative stress signalling pathway." (PMID 35662276, 2022). "Our findings highlighting NOX5 together with NOX4 in VSMC dysfunction in hypertension have clinical relevance because these NOX isoforms have been identified as novel BP-related genes." (PMID 34320175, 2022). "Docetaxel induced endothelial dysfunction and hypertension in mice, and these were prevented in Nox4–/– mice and by pharmacological inhibition of Nox4 or Rock." (PMID 35617030, 2022).